CCL28 (C-C motif chemokine ligand 28)
Diseases named in the same sentence as CCL28 in open-access papers (continued):
Sharing a sentence is not in itself a finding about the gene and the disease.
systemic lupus erythematosus (1 paper, 2024). An autoimmune multi-organ disease typically associated with vasculopathy and autoantibody production. "Additionally, a study on systemic lupus erythematosus (SLE) patients identified a mucosal phenotype of circulating plasmablasts that express the chemokine ligand CCL28, release IgA and IgG, and move to mucosal locations." (PMID 39290700, 2024).
thyroid cancer (1 paper, 2023). "The roles of CCL20 and CCL28 in small intestinal and thyroid cancer remain insufficiently investigated, while our findings demonstrate their potential as protective factors, which might provide valuable insights for future research endeavors." (PMID 38075694, 2023).
tumor (135 papers, 2013 to 2026). "Here, we noted an augmentation in pericyte accumulation within the tumor microenvironment associated with the overexpression of CCL28." (PMID 39075504, 2024). "Knockdown of CCL28 inhibited cell colony formation and invasion and counteracted miR‐612 inhibitor‐caused tumour‐promoting effects in NSCLC cells." (PMID 39632285, 2024). "Knockdown of CCL28 inhibited cell colony formation and invasion and counteracted miR‐612 inhibitor‐caused tumour‐promoting effects in PC‐9 and 95D cells." (PMID 39632285, 2024). "Knockdown of CCL28 inhibited cell proliferation and invasion and counteracted miR‐612 inhibitor‐caused tumour‐promoting effects." (PMID 39632285, 2024). "It has also been shown, consistent with our findings, that high levels of chemokines CCL4, CCL22, and CCL28 in pre-treatment tumor specimens were associated with worse patient overall survival after immunotherapy in RCC." (PMID 38067341, 2023). "Mounting evidences suggests the prime role of hypoxia in stimulating the secretion of cytokines and chemo- attractants from cancer cells and tumor associated macrophages, including CCL28, CCL22 and IL-10, that recruit Treg cells from the circulation." (PMID 37056346, 2023). "Previous reports have shown that CCL28 is not only implicated in mucosal immunity but also involved in tumour immunosuppression." (PMID 37380804, 2023). "In particular, increased serum levels of CCL28 seem to be of relevance here, as there is an association with tumor diseases in humans." (PMID 34945206, 2021). "Treg cells reach the tumor lesions by sensing CCL22, mainly produced by tumor associated macrophages (TAMs) and cancer cells, and CCL28, found in tumor hypoxic regions." (PMID 30591657, 2018). "Furthermore, a recent study has suggested that CCL28 deficiency significantly attenuates the growth of subcutaneous tumours in both immunocompetent syngeneic mice and immunodeficient NOD-SCID mice." (PMID 37380804, 2023). "It has been reported that CCL28 can recruit Treg cells, causing tumour immunosuppression." (PMID 37380804, 2023). "The hypoxic tumour microenvironment upregulates the expression of CCL28 in many tumours and thereby promotes the infiltration of CCR10 expressing Treg cells, which secrete vascular endothelial growth factor A (VEGF-A) and promote angiogenesis and metastasis." (PMID 40852716, 2025). "Overall, CCR10–CCL27/CCL28 signaling exerts diverse, context-dependent roles in cancer promoting immune cell recruitment, tumor growth, invasion, angiogenesis, drug resistance, and immune evasion, while in some cases correlating with favorable outcomes." (PMID 41050670, 2025). "Among them, the high expression of CCL4/CCL11/CCL28 is closely related to the prolonged survival period of patients, suggesting its potential for tumor suppression." (PMID 41445742, 2025). "Tumor-derived CCL28 recruits CCR10 Treg cells in ovarian cancer, promoting angiogenesis and immune tolerance under hypoxia." (PMID 41050670, 2025). "The blockade of the β-catenin/CCL28 axis releases immunosuppression and promotes anti-tumor responses within the tumor." (PMID 41396345, 2025). "In contrast, CCL28 has been identified as a negative regulator of tumor growth and bone invasion in oral squamous cell carcinoma." (PMID 39075504, 2024). "Our findings indicated that compared to the control group, tumor hypoxia significantly increased in tumors with CCL28 knockout." (PMID 39075504, 2024). "PAN-CK, NG2, CD31, and CCL28 were stained in tumor tissues to analyze their expression levels with the therapeutic efficacy of bevacizumab treatment." (PMID 39075504, 2024). "The percentage of pericyte coverage and microvessel density (MVD) in A549-CCL28 tumor tissue significantly increased compared to A549-NC, and this effect was reversed after CCL28 was knocked out." (PMID 39075504, 2024). "Further, we investigated the role of CCL28 in tumor growth and vascular normalization in immunocompetent mice." (PMID 39075504, 2024).
tumor (continued). "Both in vivo and in vitro experiments collectively illustrate that CCL28 derived from tumor cells is pivotal in advancing vascular normalization by mobilizing and reprogramming pericytes." (PMID 39075504, 2024). "In conclusion, we elucidated that a specific chemokine CCL28 induced after anti-angiogenesis therapy can alter tumor stromal cell metabolism and reshape the tumor microenvironment." (PMID 39075504, 2024). "It has been documented that CCR10 interacts with CCL28 to promote plasma cell metastasis into the tumor stroma." (PMID 39835121, 2024). "CCL28 released by hypoxic tumor cells recruits CCR10+ Tregs, promoting tumor progression and angiogenesis." (PMID 39000453, 2024). "To more clearly explore the function of CCL28 on stromal cells and immune cells in the tumor microenvironment, we performed single-cell sequencing analysis on tumor tissues of LLC-NC and LLC-CCL28." (PMID 39075504, 2024). "The secretion of IGFBP2 and CCL28 by miR-125bHigh altruists to induce tumor-wide chemorefractoriness is an oncogenic process, while cell cycle inhibition by high miR-125b expression in the altruists is a tumor suppressive event." (PMID 38093346, 2023). "The up-regulation of CCL28 in tumour cells has been shown to facilitate Treg cell infiltration into tumour tissues, thus creating an immunosuppressive microenvironment that favours tumourigenesis." (PMID 37380804, 2023). "TCGA bulk RNA-seq also showed higher CCL28 expression in PDAC tumour tissues than in normal tissues and was positively correlated with FOSL2." (PMID 37380804, 2023). "Immunofluorescence staining for CD31 indicated increased angiogenesis in oe-FOSL2 tumour but was reversed with anti-CCL28-treated tumours." (PMID 37380804, 2023). "In conclusion, these results suggested that CCL28 mediated FOSL2-driven tumour growth and Treg cell infiltration." (PMID 37380804, 2023). "Recent findings have also positively correlated overexpression of CCL28 expression with enhanced tumor growth and migration in breast cancer." (PMID 36841432, 2023). "Blockade of the β-catenin/CCL28 axis releases the immunosuppression to enhance the intra-tumoral anti-tumor response, which decreases CRC progression under HFD treatment." (PMID 36765047, 2023). "Hypoxia induced HIF-1α results in increased expression of FOXP3 in Treg cells and at the same time, also promotes CCL28 in the tumor microenvironment." (PMID 37056346, 2023). "The results of rock curve analysis demonstrated that the differential expression of SYNPO2, NR3C2, and CCL28 had a major role in distinguishing tumour tissues from borderline samples." (PMID 38081950, 2023). "CCL28 upregulation is under the control of HIF-1α, and the alleviation of hypoxia by TVN will reduce HIF-1α, abrogating CCL28 tumor-promoting effects, which leads to the inhibition of tumor growth." (PMID 37631236, 2023). "The increase of intra-tumor FOXP3+ Treg cells caused by BF BSHhigh colonization was partially reversed by blocking CCL28, confirming a vital role for CCL28 in recruiting intra-tumor FOXP3+ Treg cells during CRC progression." (PMID 36765047, 2023). "For example, in the presence of C-C Motif Chemokine Ligand 22 (CCL22) and C-C Motif Chemokine Ligand 28 (CCL28), Tregs are further promoted into the tumor cells." (PMID 36569915, 2022). "Tregs exert significant effects on inhibiting the function of IFN-γ-expressing CD4+ Th1 cells and producing the secretion of VEGF through hypoxia-mediated CCL-28, which both strikingly result in a pro-angiogenic tumor microenvironment." (PMID 36439137, 2022). "CCL28 in straight epithelial cells, as a chemokine, can recruit Treg lymphocytes and plays a key role in inflammation-induced tumor progression." (PMID 35252182, 2022). "Hypoxia-induced C-C motif chemokine ligand 28 (CCL28) promotes tumor immune evasion by attracting C-C motif chemokine receptor 10 (CCR10)-positive Tregs to the tumor site." (PMID 36072596, 2022).
tumor (continued). "Tumor hypoxia results in expression of CCL28, which promotes the recruitment of CD4+CD25+FOXP3+ Treg cells by binding to the corresponding receptor, CCR10, on Treg cells." (PMID 35759090, 2022). "It induces the upregulation of chemokines such as chemokine (C-C motif)-ligand (CCL)-22 and CCL28, that recruit Tregs at tumor sites, altering the equilibrium between T-effectors and Tregs." (PMID 36294987, 2022). "Under hypoxia, tumor cells recruit Tregs by upregulating the expression of chemokine ligand 28 (CCL28), enhancing tumor immune tolerance and promoting angiogenesis." (PMID 35493517, 2022). "For Ccl5, Ccl22, Ccl27a, Ccl28, and Cxcl12, chemokines known to exert pro-tumor effects, substantially higher levels were noted in the liver." (PMID 33985562, 2021). "IL-2 can activate nature killer (NK) cells to secrete CCL28, thus enhancing the targeted killing of tumor cells." (PMID 34307161, 2021). "CCL28 was mainly produced by tumor cells and promoted the recruitment of CCR10+ Treg cells, which supported immune tolerance by suppression of cytotoxic CD8+ T cells." (PMID 34503058, 2021). "Tumor hypoxia switches on CCL28 expression and promotes immune tolerance and angiogenesis to support tumor growth." (PMID 34503058, 2021). "CCR10 interacted with CCL28 to mediate the recruitment of Treg into tumors and accelerated tumor progression." (PMID 33868236, 2021). "In a murine model of ovarian cancer, the overexpression of CCL28 by tumor cells favors a preferential recruitment of CCR10+ Tregs, resulting in an accelerated tumor growth." (PMID 33924428, 2021). "It has been found that tumour hypoxia can promote recruitment of regulatory T(Treg) cells by inducing the expression of the chemokine CC‐chemokine ligand 28 (CCL28), which in turn facilitates immune tolerance and angiogenesis." (PMID 34120414, 2021). "In summary, metabolic signaling pathways and the CCL28 chemokine axis are prospective mechanisms that mediate the crosstalk between MDSC accumulation in the primary tumor and pre-metastatic liver." (PMID 33833986, 2021). "As expected, the expression of CCL14, CCL25, CCL26, and CCL28 were obviously related to the pathological stage, and with the aggravation of tumor malignancy, the expression of CCL25, CCL26, and CCL28 were increased while CCL14 was decreased." (PMID 34938730, 2021). "In contrast, in human ovarian and liver tumors, hypoxia favors the production of high CCL28 levels by tumor cells that are correlated with poor patient survival and with the recruitment of CCR10-expressing Tregs in the TME." (PMID 33924428, 2021). "Other hypoxia-induced molecules, such as, CCL28, recruit CC chemokine receptor 10-positive Tregs to the tumor region and facilitate tumor immune evasion." (PMID 32775303, 2020). "Regarding CCL28, recent studies have found that blocking of β-catenin–CCL28 can reduce Treg cell infiltration and inhibit tumor growth." (PMID 33034614, 2020). "For this reason, some researchers suggest that CCL28 can act locally, especially in the hypoxic regions of the tumor." (PMID 33076281, 2020). "In ovarian cancer, Tregs were selectively recruited into the tumor tissue via CCL22 and CCL28 production by the tumor cells and subsequently, Treg-induced secretion of high amounts of VEGF-A to promote endothelial cell proliferation." (PMID 33343570, 2020). "In a xenograft model of liver cancer, CCL28 upregulation promoted tumour growth and Treg recruitment in vivo in a HIF-1α dependent manner." (PMID 31835751, 2019). "Hypoxia promotes tumor angiogenesis and tolerance by inducing the expression of the chemokine CCL28, which recruits Tregs to the tumor." (PMID 31261963, 2019). "Tumour hypoxia has been implicated in promoting the generation and the recruitment of Tregs via the production of TGF-β and chemokine ligand 28 (CCL28)." (PMID 31835751, 2019). "Consistent with the results in tumor cell lines, expression of CCL28 was also highly up-regulated by hypoxia in adenocarcinoma tumor tissues." (PMID 27250766, 2016).
tumor (continued). "It remains to be elucidated, however, that how CCL28-mediated Treg-recruitment can promote tumor growth." (PMID 27716621, 2016). "In ovarian cancer, CCL28 has been suggested to mediate the recruitment of the Treg cells to the tumor site." (PMID 27716621, 2016). "We have provided evidence that liver tumor cells overcome disadvantaged hypoxic microenvironment by upregulating expression of CCL28 to recruit a specific Treg population at the tumor site." (PMID 27716621, 2016). "Results showed that CCL28 expression group produced more vessels in tumor tissue compared with control group." (PMID 27716621, 2016). "Specifically, we demonstrate that tumor hypoxia can induce elevated expression of CCL28 through HIF1α." (PMID 27716621, 2016). "CCR10, the receptor for the chemokines CCL27/CTACK and CCL28/MEC, belongs to the chemokine receptor subfamily of GPCRs and is thought to function in immune responses and tumour progression." (PMID 26941067, 2016). "Reversely, A549 and SPC-A1 cells, with CCL28 expression knock down had a lower rate of tumor formation in BALB/c nude mice (n = 3, repeated twice) and there was a lower level of tumor microvascular density in CCL28 knockdown tumors (p < 0.05)." (PMID 27250766, 2016). "As we expected, flow cytometry analysis showed that the frequency of Tregs in tumor tissues was increased in CCL28 expression group." (PMID 27716621, 2016). "Further experiments indicated that CCL28 also plays key roles in tumor angiogenesis by targeting chemokine receptor CCR3 on vascular endothelial cells." (PMID 27250766, 2016). "In a mouse ovarian cancer model, tumor hypoxia resulted in the recruitment of Tregs through upregulation of the chemokine ligand 28 (CCL28), leading to increased tumor growth." (PMID 26442214, 2015). "The secretion of chemokines, like CCL22 and CCL28, by tumor cells and the microenvironment contribute to the recruitment of immunosuppressive cells in the tumor." (PMID 24734218, 2014). "CCL28 derived from tumor cells has also been shown to promote the recruitment of Tregs and thereby promote tolerance of tumor and angiogenesis." (PMID 25937967, 2014). "Tumor hypoxia can robustly induce expression of the CC-chemokine ligand 28 (CCL28) by hypoxia inducible factor 1α (HIF1α) dependent mechanism." (PMID 24384839, 2013). "As expected, in vivo studies indicated that CCL28 could promote tumor growth in Lewis lung adenocarcinoma (LLC)." (PMID 39075504, 2024). "For instance, CCL28 may contribute to inhibiting tumor growth and dissemination by bolstering the activity of T cells, as well as other integral immune cell subsets." (PMID 39267764, 2024). "This significant difference suggested that CCL28 may play a pivotal role in influencing pericyte populations within the tumor microenvironment." (PMID 39075504, 2024). "Several studies have delved into the functions of CCL28 in the tumor microenvironment." (PMID 39075504, 2024). "Knocking out CCL28 could inhibit tumor angiogenesis, and the effect was more pronounced when bevacizumab was combined." (PMID 39075504, 2024). "Because the action of CCL28 leads to vascular normalization, making the vascular network healthier and more regular, it may also increase the density and functionality of tumor blood vessels, providing more nutrients and oxygen to promote tumor growth." (PMID 39075504, 2024). "Increased CCL28 could promote tumor vascular normalization through recruiting and metabolic reprogramming pericytes in the tumor microenvironment." (PMID 39075504, 2024). "They found decreased expression of CCL28 in tumors compared to healthy surrounding tissues, suggesting that reduced recruitment of anti-tumor factors could be a mechanism in the tumorigenesis of these neoplasms." (PMID 39684268, 2024). "Knocking out CCL28 (LLC-CCL28-KO) or supplementing retinoic acid (LLC-NC + RA) could suppress tumor growth in LLC models." (PMID 39075504, 2024).